PRDM1 (PR/SET domain 1)
Diseases named in the same sentence as PRDM1 in open-access papers (continued):
Sharing a sentence is not in itself a finding about the gene and the disease.
cholangiocarcinoma (1 paper, 2025). A carcinoma that arises from the intrahepatic biliary tree (intrahepatic cholangiocarcinoma) or from the junction, or adjacent to the junction, of the right and left hepatic ducts (hilar cholangiocarcinoma). "In contrast, diagnosis-associated proteins include several transcription factors, including HNF4A and PRDM1, which were previously associated with cholangiocarcinoma." (PMID 40470116, 2025).
colon adenocarcinoma (1 paper, 2021). "Similar to the present results in colon adenocarcinoma, high level of PRDM1 expression was also positively associated with poor prognosis in patients with carcinomas in the ovary, cervix, bladder, and esophagus." (PMID 33972671, 2021). "Of note, patients with low expression of PRDM1 in the colon adenocarcinoma displayed highly improved survival compared to the high expression group." (PMID 33972671, 2021). "PRDM1-involved genes were selected from tissue transcriptome of CRC patients using clinical datasets and their functional evaluation with KEGG pathway analysis demonstrated the ribosome-associated events are closely linked to PRDM1 in CRC, particularly the colon adenocarcinoma." (PMID 33972671, 2021). "Taken together, high tissue expression of PRDM1 indicates the bad prognosis of patients with CRC, particularly, the colon adenocarcinoma." (PMID 33972671, 2021).
follicular lymphoma (1 paper, 2022). Follicular lymphoma is a form of non-Hodgkin lymphoma characterized by a proliferation of B cells whose nodular structure of follicular architecture is preserved. "Pan-histone deacetylase (HDAC) inhibitors have been reported to elevate PRDM1 expression levels in follicular lymphoma cells." (PMID 35572579, 2022).
heart defects (1 paper, 2024). "For congenital heart defects, we detected 34 genes harboring nonsynonymous de novo variants (nsDNVs) in two or more individuals from a set of 7,958 individuals, including the ortholog of Prdm1, which is associated with hypoplastic left ventricle and hypoplastic aortic arch." (PMID 38228144, 2024).
herpes infection (1 paper, 2020). "Our transcriptome profiling data identified the transcription factors ICOS and PRDM1 (BLIMP-1) as cooperative regulators of the co-inhibitory (exhaustion) module identified in antiviral CD8+ T cells associated with asymptomatic herpes infection." (PMID 32796943, 2020).
Hyperinsulinemia (1 paper, 2024). An increased concentration of insulin in the blood. "Accordingly, hyperinsulinemia maintained its immunosuppressive effect in CD4+ cells of the JAKi-treated patients by mitigating upregulation of the key Th1 transcription factors RORC and PRDM1, as well as the chemokine receptors CXCR3 and CCR5." (PMID 39768214, 2024).
hypoplastic left heart syndrome (1 paper, 2024). Hypoplastic left heart syndrome (HLHS) refers to the abnormal development of the left-sided cardiac structures, resulting in obstruction to blood flow from the left ventricular outflow tract. "Finally, another SCG, Prdm1, is associated with hypoplastic left heart syndrome and with hypoplastic aortic arch (MGI: J:175213)." (PMID 38228144, 2024).
infectious diarrhea (1 paper, 2025). "Our data show that Prdm1 suppresses IFN-γ-mediated gene transcription, and its induction inhibits IFN-γ-stimulated cell-intrinsic defense against Cryptosporidium, an apicomplexan parasite and a leading cause of infectious diarrhea and diarrheal-related death in young children worldwide." (PMID 40497734, 2025).
intestinal cancer (1 paper, 2021). "Ribosomal dysfunction increased the marker levels of intestinal cancer cell stemness (CD133-positives) in PRDM1-dependent way in cancer spheroids under the stress of ribosomal inactivation." (PMID 33972671, 2021). "Stress-driven ribosomal dysfunction enhanced PRDM1 levels in intestinal cancer cells, which contributed to their survival and enhanced cancer cell stemness against cancer treatment." (PMID 33972671, 2021). "We next performed comparative genome-wide microarray analysis in PRDM1-suppressed HCT-8 intestinal cancer cells to investigate the molecular mechanism of PRDM1-mediated cell survival in association with ERK1/2 signals." (PMID 33972671, 2021). "The link of PRDM1 to cancer stemness was also verified in the ribosome-inactivated intestinal cancer." (PMID 33972671, 2021). "In addition to the tissue levels, the in vitro ribosomal dysfunction enhanced PRDM1 mRNA levels in different types of intestinal cancer cells." (PMID 33972671, 2021). "Moreover, ribosomal dysfunction-induced PRDM1 was dependent on PKR as a central eIF2α kinase of integrated stress responses in the intestinal cancer cells." (PMID 33972671, 2021).
intestinal tumor (1 paper, 2021). "Therefore, it was hypothesized that PRDM1 is involved in stress responses of the intestinal tumor cells." (PMID 33972671, 2021).
lentivirus infection (1 paper, 2024). Virus diseases caused by the Lentivirus genus. "Notably, we also observed an overproduction of photoreceptor cells, as evidenced by an increased count of PRDM1+ cells at both developmental stages, following lentivirus infection." (PMID 39012348, 2024).
lung fibrosis (1 paper, 2021). "Adoptive transfer experiments of B cell-specific Blimp1 CKO mice (PRDM1 CKO) induced skin sclerosis and lung fibrosis." (PMID 34854378, 2021).
Lymphadenopathy (1 paper, 2017). Enlargement (swelling) of a lymph node. "Similarly, 100% of Prdm1 cKOFoxN1 mice analyzed developed lymphadenopathy, albeit at a slightly later time point (≥5 mo)." (PMID 28701508, 2017).
mantle cell lymphoma (1 paper, 2020). Mantle cell lymphoma is a rare form of malignant non-Hodgkin lymphoma affecting B lymphocytes in the lymph nodes in a region called the ``mantle zone''. "It has been demonstrated that functional PRDM1 is required for mantle cell lymphoma response to bortezomib, while loss of PRDM1 was found in more than half of the patients with ABC-DLBCL, which may hinder the apoptosis induced by bortezomib." (PMID 33317571, 2020).
metastatic disease (1 paper, 2024). "Using immunohistochemical staining of 170 ccRCC patients, VEGFR1 (FLT1) expression was associated with treatment response, histological grade and RECIST (Response Evaluation Criteria in Solid Tumors) score, whereas SAV1 and BLIMP1 (PRDM1) were associated with metachronous metastatic disease." (PMID 38999991, 2024).
Primary amenorrhea (1 paper, 2020). "One novel heterozygous missense variant in PRDM1 was found in POI-37, who was diagnosed at 14 years of age presenting with primary amenorrhea, delay of puberty, cafe au lait spots, high arched palate, cubitus valgus, hyperdontia, and congenital heart defect." (PMID 33095795, 2020).
retinal dystrophies (1 paper, 2025). "We found downregulation of Prdm1—a photoreceptor marker—and Nr2e3—a key regulator of photoreceptor specification also implicated in retinal dystrophies—as well as effects on NR2E3’s direct and indirect targets." (PMID 40824246, 2025). "Markedly, we found that PRDM13 expression downregulated the photoreceptor marker Prdm1 as well as Nr2e3—a key regulator of photoreceptor specification also implicated in retinal dystrophies—and affected NR2E3’s direct and indirect targets." (PMID 40824246, 2025).
sarcoidosis (1 paper, 2025). Sarcoidosis is a multisystemic disorder of unknown cause characterized by the formation of immune granulomas in involved organs. "Additionally, CD4+ T cells from sarcoidosis patients exhibited increased PRDM1 and GATA3 expression, while naive markers SELL, TCF7 and LEF1 were reduced in sarcoidosis and active TU compared with healthy donors." (PMID 40469525, 2025).
skin inflammation (1 paper, 2017). "Given the similarities between skin and the thymic epithelium and the models used to describe the roles of skin inflammation with age in Prdm1 conditional knockout (KO) (cKO) mice, we sought to determine whether Prdm1 influences thymic epithelial function." (PMID 28701508, 2017). "Mice lacking Prdm1 in epithelial cells develop chronic skin inflammation, which is thought to be due to defects in epidermal barrier immunity." (PMID 28701508, 2017).
spinocerebellar ataxia type 1 (1 paper, 2024). Spinocerebellar ataxia type 1 (SCA1) is a subtype of type I autosomal dominant cerebellar ataxia (ADCA type I) characterized by dysarthria, writing difficulties, limb ataxia, and commonly nystagmus and saccadic abnormalities. "Strikingly, PRDM1 transcription factor was found to interact with 82Q ATXN1, the mutant protein in spinocerebellar ataxia type 1 (SCA1), and has been found to be expressed at the granule and Purkinje cells of the cerebellum during chicken embryonic and germline development." (PMID 38396267, 2024).
testis cancer (1 paper, 2022). "To address this, we analyzed the correlation between NANOS1 and NANOS3 with its upstream transcriptional program in human primordial germ cells including transcription factors PRDM1, SOX17, TFAP2C, and PRDM14 expression in testis cancer samples." (PMID 36012673, 2022).
thymoma (1 paper, 2023). A neoplasm arising from the epithelial cells of the thymus. "Specifically, we measured the Spearman correlation coefficient R to evaluate the expression correlation of PRDM1, PRDM2 and their main transcripts on three datasets from The Cancer Genome Atlas (TCGA) and Genotype-Tissue Expression (GTEx): whole blood, thymoma normal and EBV-transformed lymphocytes." (PMID 36964555, 2023).
trisomy 16 (1 paper, 2024). "In this work, it was shown that in the studied group of spontaneousabortions with trisomy 16, the level of methylationof the PRDM1 and PSG2 genes was significantly increasedcompared with induced abortions." (PMID 38680176, 2024).
Waldenstrom macroglobulinaemia (1 paper, 2022). "PRDM1 is also downregulated in patients with Waldenstrom macroglobulinaemia, which is linked to elevated expression of the negative regulator SPIB." (PMID 35831623, 2022). "Our results revealed that Ezh2 inhibition increases PRDM1 and downregulates SPIB, suggesting that further investigation of Ezh2 inhibitors in the context of ABC DLBCL and Waldenstrom macroglobulinaemia could be informative." (PMID 35831623, 2022).
Warthin tumor (1 paper, 2024). An adenoma characterized by an oncocytic, often papillary, epithelial component, dense lymphoid stroma, and cystic spaces. "The results indicate a significant role of the PRDM1 protein in the development of Warthin’s tumors, which may serve as a target for diagnosis and treatment." (PMID 39684268, 2024).
tumor (191 papers, 2013 to 2026). "Based on gene enrichment analysis, PRDM1 was implicated in many pathways involved in tumor progression." (PMID 35607327, 2022). "Nevertheless, our findings underscore the need to balance a reciprocal upregulation of NR4A3 and NFAT signaling in the setting of PRDM1 deficiency to generate effective CAR T-cell-mediated responses in a variety of tumor types." (PMID 36350986, 2022). "This decrease in cytotoxic protein expression led to delayed tumor clearance, which caused PRDM1 KO CAR T-cells to be exposed to target cancer cells for twice as long as control CAR T-cells." (PMID 36350986, 2022). "Transcriptomic dataset analysis demonstrated that tumor-derived PRDM1 was positively associated with expression of Sox-9, a well-known modulator of cancer progenitor cells in CRC." (PMID 33972671, 2021). "As revealed by comparative genomic hybridization, 6q21 is frequently deleted in NKTCL, leading to the loss of tumor suppressor genes located in this region, including PRDM1, ATG5, AIM1, FOXO3, and HACE1." (PMID 30514323, 2018). "This 6q21 deletion leads to the loss of expression of several tumour suppressor genes including PRDM1, ATG5, AIM1, FOXO3 and HACE1." (PMID 28893938, 2017). "While NF-κB signalling is constitutively active, most ABC DLBCLs carry either inactivating point mutations, deletions or epigenetic silencing of the PRDM1 gene, and consequently tumour cells are driven to accumulate at the plasmablast stage." (PMID 28893938, 2017). "Exon 3 frameshift mutation of PRDM1 gene p.G100Efs11, which may be involved in tumor development." (PMID 37884941, 2023). "In addition to the tumor growth promotion, stress-linked PRDM1 may play crucial roles in cancer cell survival from adverse environment including anticancer actions of chemotherapeutics." (PMID 33972671, 2021). "PRDM1 has also been identified as a tumor suppressor that is frequently inactivated/lost in NK-cell malignancies." (PMID 41366532, 2026). "Collectively, these findings demonstrate that PRDM1 acts as a tumor suppressor in BCa by inhibiting OTUD6A transcription and promoting CDC6 degradation." (PMID 41724787, 2026). "PR domain-containing protein 1 with a zinc finger domain (PRDM1) is a tumor regulator in many types of cancer." (PMID 41693648, 2026). "A study in tumor infiltrating lymphocytes revealed the transcriptional regulation of co-inhibitory receptors by PRDM1." (PMID 41366532, 2026). "PRDM1 mediates stress‐induced ribosomal dysfunction, driving tumor cell survival and stemness via insulin‐like growth factor receptor pathway reprogramming." (PMID 41562159, 2026). "In vivo, Prdm1-cKO in Treg cells suppressed tumor growth, improved prognosis, and decreased Treg cell infiltration." (PMID 40436857, 2025). "PRDM1 possibly facilitates tumor immune evasion by elevating PD-L1 expression, thereby blunting anti-tumor effects." (PMID 41394809, 2025). "In EBV-infected B-cells, IRF4 and BATF jointly repress tumor suppressors like PRDM1 and BCL2L11, thereby promoting transformation." (PMID 40313738, 2025). "The PRDM protein family, including members such as PRDM2 and PRDM16, showcases a similar yin-yang paradigm in tumor contents observed in PRDM1, characterized by two functionally antagonistic isoforms originating from a single gene." (PMID 39562537, 2024). "Bulk RNA sequencing of splenic cNK cells (CD3-NK1.1+NKp46+) was conducted to uncover the molecular mechanisms by which Prdm1 regulates NK cell anti-tumor immunity." (PMID 39133873, 2024). "Genetic knock-out of PRDM1 in CAR-T cells targeting multiple tumour-bearing models facilitated a memory phenotype and prevented T cells from gaining terminal differentiated subtypes, highlighting PRDM1 as a promising target to improve the efficacy of ACTs." (PMID 38581063, 2024). "Histological analysis further confirmed the increased frequency of metastasis tumor foci in Prdm1 cko mice." (PMID 39133873, 2024).
tumor (continued). "Using Ncr1-driven conditional knockout transgenic mice, which specifically delete Prdm1 in group 1 ILCs, we not only validated Prdm1’s positive regulation of NK cell maturation, but also demonstrated its indispensable role in NK cell anti-tumor activity." (PMID 39133873, 2024). "Tumor cells overexpressing PRDM1 can upregulate PD-L1 expression, leading to tumor immune escape and suppression of tumor immunity." (PMID 39289763, 2024). "(E) Percentages of IFN-γ+ liver cNK cells and ILC1s from Prdm1+/+ and Prdm1 cko tumor-bearing mice (n=5)." (PMID 39133873, 2024). "The test results showed that the tumor-specific mutations in this sample were as follows: BCL6, TNFAIP3, PRDM1, CREBBP, DTX1, and FOXO1." (PMID 37884941, 2023). "In experimental tumour models, cMaf and Prdm1 were identified as cooperative regulators of coinhibitory receptor expression by T cells." (PMID 36594463, 2023). "Next-generation sequencing revealed six tumor-specific mutated genes (IGH/BCL6, TNFAIP3, PRDM1, CREBBP, DTX1, and FOXO1)." (PMID 37884941, 2023). "In contrast, PRDM1/NR4A3 KO CAR T-cells demonstrated a significant reduction in the proportion of PD-1+TIM-3+ CD8 T-cells in both the tumor (P < 0.05) and peripheral blood as compared to AAVS1 KO CAR T-cells (P < 0.01)." (PMID 36350986, 2022). "Consistent with these previous studies, the cytotoxic capacity and effector cytokine production of PRDM1 KO CAR T-cells were substantially compromised compared to conventional CAR T-cells after multiple rounds of tumor antigen exposure." (PMID 36350986, 2022). "In summary, we identified that tumoral PRDM1/BLIMP1 overexpression is a double-edged sword in regulating tumor growth." (PMID 36509766, 2022). "More importantly, combined treatment with Prdm1 overexpression and PD-1 mAb further impaired tumor proliferation and prolonged survival time compared with that in Prdm1 overexpression or PD-1 mAb treatment alone." (PMID 36509766, 2022). "We found that PRDM1/NR4A3 double KO significantly increased the absolute numbers of CAR T-cells in the tumor (P < 0.05) and peripheral blood (P < 0.001) compared to AAVS1 KO CAR T-cells fig." (PMID 36350986, 2022). "It has been suggested that overexpression of PRDM1 inhibits cell proliferation, cell cycle arrest and enhances apoptosis of tumor cells." (PMID 35927251, 2022). "Bioluminescent tumor burden was also significantly decreased by a single infusion of PRDM1/NR4A3 KO PSMA CAR T-cells compared to AAVS1 KO (P < 0.05) CAR T-cells in mice bearing intraosseous tumors generated by PC3-PSMA cell engraftment." (PMID 36350986, 2022). "Ultimately, as expected, patient 2 with high tumoral PRDM1 expression showed significant tumor shrinkage after treatment, whereas patient 1 with low tumoral PRDM1 expression showed tumor progression after treatment." (PMID 36509766, 2022). "In this study, only PRDM1/NR4A3 double knockout anti-mesothelin CAR T-cells mediated a significant reduction in tumor burden over time (P < 0.05, fig." (PMID 36350986, 2022). "To investigate the effects of PRDM1 on the transcriptome of tumor-infiltrating T cells, we conducted unbiased secondary clustering of the T cell population." (PMID 36509766, 2022). "PRDM1/NR4A3 dual KO CAR T-cells demonstrated better control of tumor growth than control CAR T-cells following rechallenge." (PMID 36350986, 2022). "Further, after five consecutive tumor challenges, the cytolytic activity of PRDM1 KO CAR T-cells was impaired compared to that of control CAR T-cells." (PMID 36350986, 2022).